MYD88 (MYD88 innate immune signal transduction adaptor)
Diseases named in the same sentence as MYD88 in open-access papers (continued):
Sharing a sentence is not in itself a finding about the gene and the disease.
pneumonia (35 papers, 2008 to 2025). An acute, acute and chronic, or chronic inflammation focally or diffusely affecting the lung parenchyma, caused by an infection in one or both of the lungs (by bacteria, viruses, fungi, or mycoplasma.). "Accordingly, while Myd88 deficiency resulted in markedly reduced purulent meningitis compared with WT mice, Myd88–/– mice exhibited an even more pronounced pneumonia secondary to meningitis than their corresponding WT counterparts." (PMID 38358825, 2024). "Nonetheless, in a recent study on a pediatric cohort of IEI patients, two young brothers with Myd88 deficiency developed pneumonia requiring hospital admission in both cases and oxygen administration in one case." (PMID 35445287, 2022). "Upon challenge with C. pneumoniae MyD88-deficient mice succumbed like TLR2/4-deficient mice to progressive pneumonia, although pulmonary IFNγ-levels were increased like in wild type mice six days post infection." (PMID 22096480, 2011). "A recent study on various murine models, such as healthy immunocompetence, MyD88-deficiency, lymphocyte-deficiency, and neutrophil-depletion, indicated that neutrophil-phage synergy is essential for infection clearance and the resolution of pneumonia." (PMID 37766890, 2023). "Thus, the mechanisms underlying the hypersusceptibility of TLR7/9/13 triple KO mice to pneumonia are similar to those previously identified in MyD88-deficient mice, in which chemokine production and neutrophil recruitment to the lung were severely impaired." (PMID 32209688, 2020). "Hence, in the present study we investigated the host response during pneumonia caused by the serotype 2 strain D39 and an isogenic capsule locus (cps) deletion mutant of D39 (D39Δcps) in both wild type (WT) and Myd88-/- mice." (PMID 25700108, 2015). "Other genes involved in immune response are MYD88, a candidate gene for resistance to small ruminant lentiviruses, and FOCF1, linked to pneumonia resistance." (PMID 41273432, 2025). "When dysregulated, lung commensal bacteria such as Bacteroides and Prevotella can provoke macrophages to produce IL17B via toll-like receptor (TLR)–Myd88 signaling, accelerating pneumonia and fibrosis as a result." (PMID 39010112, 2024). "As a critical transmembrane recognition receptor of the innate immune system, TLR4 is involved in the occurrence of pneumonia and other inflammatory diseases, and NF-κB and MyD88 are its downstream molecules." (PMID 39472001, 2024). "The inhibition of ‘cytokine storm’ via the regulation of TLR7/MyD88 signaling pathway was suggested as a potential mechanism of FFYH against influenza pneumonia." (PMID 37089926, 2023). "Our findings revealed that LNT reduces the severity of pneumonia induced by IAV infection by modulating the TLR4/MyD88 signaling pathway, resulting in a more effective therapeutic impact." (PMID 35669119, 2022). "TLR4/MyD88 was shown to activate the nuclear factor-kappa B (NF-κB) inflammatory pathway in enteritis, promote myocardial infarction and induce acute pneumonia." (PMID 34589510, 2021). "Our findings demonstrated that anemoside B4 attenuates pneumonia via the TLR4/Myd88 signaling pathway, suggesting that anemoside B4 is a promising therapeutic candidate for bacterial-infected or viral-infected pneumonia." (PMID 32625244, 2020). "Taken together, anemoside B4 ameliorated FM1-induced pneumonia via the TLR4/MyD88 pathway with binding to TLR4." (PMID 32625244, 2020). "In summary, our study demonstrated that anemoside B4 exhibited significant protective effects on Klebsiella pneumoniae- or influenza virus FM1 induced pneumonia via theTLR4/Myd88 signaling pathway." (PMID 32625244, 2020). "To obtain insight in the role of MyD88 dependent platelet signalling in systemic coagulation activation during ΔcpsD39 pneumonia, we measured TATc levels in plasma of infected Plt-Myd88-/- and control mice." (PMID 27253707, 2016).
pneumonia (continued). "Platelets have been shown to be important in the host defence to S. pneumoniae pneumonia and the unencapsulated serotype 2 strain D39 (ΔcpsD39) is cleared in a MyD88 dependent manner." (PMID 27253707, 2016). "We here sought to determine the role of pneumococcal capsule in MyD88-mediated antibacterial defense during S. pneumonia pneumonia." (PMID 25700108, 2015). "Taken together, the present study showed that early MJWQH treatment contributed to recovery from severe pneumonia due to its anti-inflammatory activity through regulating TLR7/MyD88/NF-κB signaling pathway." (PMID 26089947, 2015). "Our findings reveal that the polysaccharide capsule partially protects pneumococci against MyD88-mediated immunity during pneumonia in mice." (PMID 25700108, 2015). "Notably, global MyD88 deficiency similarly results in an early impairment of neutrophil chemoattractant release and neutrophil migration into the airways in mouse models of pneumonia caused by a variety of bacterial and viral species, as well as during sterile lung inflammation." (PMID 25254554, 2014). "Vaccination of MyD88-deficient mice with M. bovis BCG induced IFNγ-producing CD4+ T-cells in vivo, but the TH1 cells only partially prevented lethal pneumonia upon challenge with M. tuberculosis." (PMID 22096480, 2011). "More specifically, our current results now further add to accumulating evidence that MyD88 is necessary for neutrophil recruitment during pneumonia." (PMID 18946505, 2008). "Homozygous MYD88 E65del mutation (also known as p.Glu52del) has been linked to early SBIs (meningitis, pneumonia, and abscesses) with absent inflammatory markers." (PMID 41479884, 2025). "Yin-Qiao San may target some elements in the TLR7/MyD88/NF-κB pathway to achieve its therapeutic effects against influenza pneumonia." (PMID 37089926, 2023). "EBV viremia without clinical repercussions was later reported in a MyD88-deficient patient, and P5 was recently reported to have suffered from bilateral pneumonia caused by influenza A virus and the human cororonavirus NL63." (PMID 36880831, 2023). "Our results showed that compared with the Control group, the expressions of TLR4, MyD88, NF-κB, and ICAM-1 of the Model group were significantly higher (P < 0.01), indicating that the TLR4/MyD88/NF-κB signaling pathway was activated during the development of MDR PA-induced pneumonia in rats." (PMID 35071595, 2022). "However, TLR2-induced MyD88 activation is known to trigger an important inflammatory immune response and it is very critical for the clearance of P. aeruginosa-induced pneumonia." (PMID 34737734, 2021). "Therefore, anemoside B4 exhibited a significant therapeutic effect on pneumonia via the TLR4/MyD88 pathway." (PMID 32625244, 2020). "Both MyD88‐ and TRIF‐dependent pathways are implicated in TLR4‐mediated lung injury in pneumonia." (PMID 31350813, 2019). "Complementary studies of a mouse model of P. aeruginosa LPS-induced acute pneumonia confirmed that RCAN1-deficient mice displayed greatly enhanced NF-κB activity and MyD88-NF-κB-mediated cytokine production, which correlated with enhanced pulmonary infiltration of neutrophils." (PMID 29799862, 2018). "For in vivo pneumonia experiments, platelet specific Myd88 knockout (Plt-Myd88-/-) mice were used." (PMID 27253707, 2016). "In accordance, Plt-Myd88-/- mice were unaffected during ΔcpsD39 pneumonia." (PMID 27253707, 2016). "Additionally, unexpectedly, a hypoxemic (P24) and non-hypoxemic pneumonia (P25) occurred in two siblings with MyD88-deficiency, an IEI that has not classically been associated with viral susceptibility." (PMID 36742319, 2023). "Therefore, HHDC may act against influenza pneumonia by regulating the TLR/MyD88/NF-κB signaling pathway." (PMID 37089926, 2023). "Therefore, anemoside B4 suppressed the FM1 or KP-induced pneumonia via the TLR4/Myd88 pathway." (PMID 32625244, 2020). "The TLR2, TLR4, and MyD88 deficiency did not alter the host response during lethal pneumonia." (PMID 32849610, 2020).
pneumonia (continued). "Previous studies have shown that AB4 alleviates pneumonia induced by Klebsiella pneumoniae and influenza virus FM1 in mice by inhibiting the TLR4/MyD88 signaling pathway." (PMID 40012747, 2025). "To establish that MyD88 are required for S. pneumoniae induced lung IFNγ, we adoptively transferred (i.n.)WT, STING−/−, or MyD88−/− monocytes to CCR2−/− mice and examined the IFNγ production in the lung by S. pneumonia." (PMID 34512626, 2021). "The TLR2-induced MyD88 activation is not required for the S. aureus clearance during pneumonia and only exerts the potent inflammatory immune response, but it plays a crucial role in P. aeruginosa clearance." (PMID 32849610, 2020). "Lastly, platelet MyD88 signalling had no influence on endothelial cell activation during ΔcpsD39 pneumonia as E-selectin levels did not significantly differ." (PMID 27253707, 2016). "While single-ligand ODN treatment significantly improved pseudomonal pneumonia survival of Tlr9–/–, Rigi–/–, and Mavs–/– mice, the same ODN treatment did not induce significant protection against pseudomonal pneumonia in Tlr9–/–;Mavs–/– or MyD88–/–;Mavs–/– double-knockout mice." (PMID 39352770, 2024). "Also, TLR2-induced MyD88 activation was not required for the clearance of S. aureus during pneumonia." (PMID 34737734, 2021). "While platelets are additionally known to regulate lung architectural changes and vascular integrity during inflammation, platelet activation via MyD88 dependent TLR signalling seems not involved as we found no histopathological differences between the groups in our pneumonia model." (PMID 27253707, 2016). "MyD88 dependent TLR signalling in platelets is not involved herein, as bacterial clearance was similar in Plt-Myd88-/- and control mice during ΔcpsD39 pneumonia." (PMID 27253707, 2016).
ischemia (34 papers, 2009 to 2025). A hypoperfusion of the BLOOD through an organ or tissue caused by a PATHOLOGIC CONSTRICTION or obstruction of its BLOOD VESSELS, or an absence of BLOOD CIRCULATION. "TLR4 has been shown to be induced in tubular epithelial cells in the kidney following ischemia in a MyD88-dependent manner, and TLR4-deficient mice are protected against tubular damage, suggesting that TLR4 promotes renal ischemia-reperfusion injury." (PMID 28542370, 2017). "At the same time, L‐F001 can inhibit the activation of TLR4/MyD88 pathway in neonatal rat HIBD model, indicating that L‐F001 plays a neuroprotective role after hypoxic‐ischemia by regulating inflammatory response through the TLR4/MyD88 pathway." (PMID 37822185, 2023). "In vivo, the expression of the TLR4/MyD88/NF-κB pathway was upregulated in the WT ischemia group and downregulated in the PCSK9−/− ischemia group." (PMID 35832650, 2022). "At both late time points, 3 (2.28-fold expression, p = 0.024) and 7 days (2.79-fold expression, p = 0.001), the Myd88 expression was still higher in the ischemia group." (PMID 32833183, 2021). "For instance, miR-203 was described as a negative regulator in ischemia, inducing microglia activation by targeting myeloid differentiation primary response 88 (MyD88) upon ischemia." (PMID 31627485, 2019). "First, PACAP1-38 seems to protect microglia in ischemia by inhibiting a microglial Toll-like receptor, MyD88 and by blocking the tumor necrosis factor α expression and NO production." (PMID 31540472, 2019). "The attenuating effect of PACAP1-38 in the kidney is attributed to the suppression of Toll-like receptor 4/MyD88 signaling, known to be responsible for ischemia-induced inflammation." (PMID 31540472, 2019). "Among the Toll-like receptors (TLR), TLR2, TLR4, and their adaptor protein, myeloid differentiation primary-response 88 (MyD88), have been reported to be involved in intestinal ischemia/reperfusion injury." (PMID 30087540, 2018). "The elevated expression of TLR4, TLR2, MyD88 and NF-κB is thought to be consistent with ischemia-evoked neuron injury and death through an inflammatory mechanism." (PMID 23434667, 2013). "Both the MyD88 and TRIF pathways are involved in TLR4-mediated brain injury in ICH, whereas only MyD88 is involved in ischemia." (PMID 23414417, 2013). "This study demonstrates a distinct pattern of cytokine/chemokine production following focal ischemia in mice with disruptions of MyD88 and TRIF." (PMID 22799573, 2012). "This is consistent with recent data suggesting that miRNA (18–23 bases) released into the circulation and extracellular space during ischemia may instead trigger cytokine production via endosomal TLR7/MyD88 signaling." (PMID 30367171, 2018). "Interestingly, while all animals in our current study demonstrated loss of nuclear HMGB1 in the setting of ischemia 4–24 h after FAL, only MyD88 KO mice and TRIF KO mice had detectable serum HMGB1 levels at these time points." (PMID 24844636, 2014). "An interesting additional finding from our study is that there is significantly increased MCP1/CCL2 expression and MPO activity in the right lung following left lung ischemia-reperfusion and that this right lung response is attenuated in Myd88-/- and, to a lesser extent Tlr4-/- mice." (PMID 24146959, 2013). "TLR2 and TRIF signaling are necessary for muscle regeneration after ischemia while MyD88 may instead mediate muscle injury." (PMID 23209800, 2012). "In this study, we have demonstrated a role for the MyD88 pathway in neutrophil migration to the site of ischemia by showing significant decreases in the levels of neutrophil chemoattractants, such as KC and G-CSF, in MyD88−/− mice following focal cerebral ischemia." (PMID 22799573, 2012). "In an effort to determine the specific contribution of myocardial MyD88 to cardiac injury following ischemia, Feng and colleagues tested whether or not MyD88 deficiency would have any effect on myocardial injury in isolated mouse hearts." (PMID 21977329, 2011).
ischemia (continued). "Our results show that after FAL, both MyD88 KO mice and TRIF KO mice have evidence of ischemia, as do their control counterparts." (PMID 24844636, 2014). "Similarly, the extracellular histone–TLR9–MyD88 pathway has been also reported in a hepatic ischemia/reperfusion injury model, as shown by the inhibitory effect of an anti-histone antibody and as observed in TLR9- and MyD88-knockout mice." (PMID 27656184, 2016). "In addition, we have also found that ischemia-induced increased expressions of TLR adaptor and signalling proteins such as MyD88 and TRAF6 were prevented by IVIg treatment." (PMID 25886362, 2015). "We have previously demonstrated that MyD88 knockout (MyD88 KO) mice tolerate hindlimb ischemia very well, showing little evidence of muscle injury (i.e., fat replacement, actively regenerating myocytes) 2 weeks after femoral artery ligation." (PMID 24844636, 2014). "Since dexmedetomidine hydrochloride was observed to mediate a protective effect against lung injury following intestinal ischemia-reperfusion, molecules upstream of the cytokines were analyzed, including the TLR4/MyD88 pathway which mediates cytokine production." (PMID 24255662, 2013). "Although endogenous ligands to TLR4 contribute to lung ischemia-reperfusion injury, the protective effect in Tlr4-/- mice on MCP-1/CCL2 expression and vascular barrier dysfunction were relatively small compared to that seen in Myd88-/- mice." (PMID 24146959, 2013). "Our previous study showed that only the MyD88 but not the TRIF pathway was involved in TLR4-mediated ischemia damage, suggesting that although TLR4 participates in both ischemia- and hemorrhage-induced brain injury, the underlying signaling pathway is different." (PMID 22394415, 2012). "Furthermore, the elevated MyD88 expression in the nonischemic limb of TRIF KO mice may suggest that MyD88 expression is higher in TRIF KO mice in response to ischemia." (PMID 24844636, 2014). "Furthermore, the TLR4/MyD88/MAPK signaling pathway was observed to be involved in the mechanism of the protective effect of dexmedetomidine on the lung following I/R injury, although an α2-adrenergic antagonist failed to neutralize the effect of dexmedetomidine on acute ischemia-induced lung injury." (PMID 24345905, 2014).
lymphoplasmacytic lymphoma (32 papers, 2014 to 2026). A clonal neoplasm of small B-lymphocytes, lymphoplasmacytoid cells, and plasma cells involving the bone marrow, lymph nodes, and the spleen. "It has been reported that MYD88 mutation was detected in the cfDNA of one patient with lymphoplasmacytic lymphoma." (PMID 35865478, 2022). "Some examples of these alterations are the detection of BRAF V600 E/K in HCL and MYD88 p.L26P mutations in lymphoplasmacytic lymphoma and Waldenstrom’s macroglobulinemia, which are considered to be disease-defining alterations." (PMID 34943410, 2021). "MYD88 mutations, particularly the L265P variant, are most commonly associated with lymphoplasmacytic lymphoma and may serve as a useful molecular marker to distinguish this entity from other small B-cell lymphomas and from plasma cell neoplasms." (PMID 40847225, 2025). "Bone marrow biopsy demonstrated lymphoplasmacytic lymphoma with MYD88 L265P mutation." (PMID 41040767, 2025). "The MYD88 p.L265P mutation is of special interest in diagnosing lymphoplasmacytic lymphoma (LPL)." (PMID 34943410, 2021). "MYD88 has also been recurrently found mutated in majority of lymphoplasmacytic lymphoma (> 90%)." (PMID 27825110, 2016). "The TBL1XR1 gene is frequently affected by mutations in ABC-DLBCL, and has been described in IVLBCL, as well as in MYD88-wild type lymphoplasmacytic lymphoma cases." (PMID 38441683, 2024). "A bone marrow biopsy confirmed MYD88-positive lymphoplasmacytic lymphoma involving ∼50% of the bone marrow cellularity." (PMID 35096069, 2022). "Anemia works up to a bone marrow biopsy which revealed a MYD88-positive lymphoplasmacytic lymphoma involving ∼90% of the bone marrow cellularity with minimal residual hematopoiesis." (PMID 35096069, 2022). "A MYD88-positive lymphoplasmacytic lymphoma was confirmed by a bone marrow biopsy involving ∼50% of the bone marrow cellularity." (PMID 35096069, 2022). "Further immunophenotypic and molecular characterization revealed a MYD88‐positive lymphoplasmacytic lymphoma." (PMID 27109862, 2016). "BM biopsy demonstrated lymphoplasmacytic lymphoma with λ-restricted plasma cells, and molecular studies were negative for MYD88 L265P and CXCR4 mutations." (PMID 42282257, 2026). "The diagnosis was confirmed via biopsy (CD20+, CD5-, CyclinD1-) and negative MYD88 L265P mutation status, excluding lymphoplasmacytic lymphoma." (PMID 41800116, 2026). "Notwithstanding, MYD88 mutated cases must be interpreted with caution, and the possibility of a lymphoplasmacytic lymphoma should be ruled out." (PMID 40282427, 2025). "The absence of MYD88 excluded lymphoplasmacytic lymphoma, and the absence of a BRAF mutation excluded hairy cell leukemia." (PMID 41531558, 2025). "MYD88 L265P is often found in lymphoplasmacytic lymphomas occurring outside the brain." (PMID 38730692, 2024). "Upon admission, hemoglobin was 7.6 g/dL and laboratory tests were consistent with cold agglutinin disease (CAD), the presence of monoclonal IgM, and flow cytometry consistent with lymphoplasmacytic lymphoma, but MYD88 L265P mutation was negative." (PMID 34201186, 2021). "Although not always encountered in the spleen, lymphoplasmacytic lymphoma, a B-cell lymphoproliferative disorder consisting of a dual population of both clonal B-cells and plasma cells and the frequent presence of the MYD88 L265P mutation, is another CD5-CD10-LPD that can be seen in the spleen." (PMID 34940069, 2021). "A bone marrow biopsy combined with immunohistochemistry confirmed the diagnosis of lymphoplasmacytic lymphoma (IgG-κ type, MYD88 L265P negative)." (PMID 41777550, 2026).